STK10 (serine/threonine kinase 10)
Diseases named in the same sentence as STK10 in open-access papers (continued):
Sharing a sentence is not in itself a finding about the gene and the disease.
tumor (continued). "In conclusion, we demonstrate that host Stk10 is involved in the host anti-tumor response by modulating the activated tumor-infiltrated CTLs and angiogenesis." (PMID 36421382, 2022). "Our data indicate that host Stk10 participates in the anti-tumor process via modulating the activated tumor-infiltrated CTLs and angiogenesis in the TME." (PMID 36421382, 2022). "The FACS results showed that the proportion of naïve CTLs was significantly increased, and the proportions of activated, effector, and even exhausted CTLs were significantly decreased in tumor tissues grown in Stk10−/− mice than those in the WT mice." (PMID 36421382, 2022). "Our data provide us with the possibility of using STK10 as a candidate target for anti-tumor immunotherapy." (PMID 36421382, 2022). "According to the data from the TIMER database, the expression of STK10 showed significant association with lymphocytes, neutrophils, macrophages and dendritic cells in PRAD tumor tissues." (PMID 36421382, 2022). "We further verified the role of Stk10 in the tumor vascular progression with a tube formation assay." (PMID 36421382, 2022). "STK10 is a key kinase for tumor progression and siRNA knockdown of STK10 increases apoptosis of tumor cells." (PMID 32471307, 2020). "STK10 is expressed in various tumor cell lines, as well as in highly proliferative normal tissue, where it co-associates with and phosphorylates Plk1." (PMID 32471307, 2020). "Although its exact function remains unclear, our study lays a solid foundation for future research on how STK10 contributes to tumor immunity." (PMID 39555062, 2024). "Notably, the current study demonstrated that the depletion of host Stk10 leads to a significant enhancement in vasculature formation in the tumor issues, as evidenced by CD31 staining." (PMID 36421382, 2022). "Moreover, Spearman’s correlation test revealed the positive correlation between these ligands on tumor cells with STK10." (PMID 35501867, 2022). "Further analysis revealed that CD4+ helper T cells (CD45+CD3+CD4+) were not significantly different between these two groups, and the percentage of tumor-infiltrated CD8+ CTLs (CD45+CD3+CD8+) was significantly higher in the Stk10−/− mice compared to that in WT mice." (PMID 36421382, 2022). "However, the impact of STK10 on the host defense against tumors remains unclear, and the biological function of STK10 in the homeostasis of the tumor microenvironment (TME) needs to be further elaborated." (PMID 36421382, 2022). "Since our data revealed that knockout of host Stk10 does not affect the cell apoptosis of CTLs, we next asked whether Stk10 participates in the activation of CTLs in response to tumors, because CTLs need to be activated in order to make efficient and durable anti-tumor immune responses." (PMID 36421382, 2022). "FPR2-dependent STK10 phosphorylation could mediate cell proliferation and tumor progression." (PMID 32471307, 2020). "Our findings suggest that the STK10 inhibitor SB633825, in collaboration with bortezomib, enhances CALR exposure, thereby demonstrating a more robust anti-tumor immune activation." (PMID 39555062, 2024). "The object of this study was to evaluate the role of serine-threonine kinase 10 (STK10) in the TME and host anti-tumor response." (PMID 36421382, 2022). "However, the correlation between STK10 and the tumor microenvironment (TME) remains unclear." (PMID 36421382, 2022). "To uncover the potential contribution of Stk10 to tumor angiogenesis, we examined the expression of CD31, a marker of vascular endothelial cells, in the tumor tissues, by using immunofluorescence analysis." (PMID 36421382, 2022). "Although the expression of LGALS9 on tumor samples was higher as well, the spearman’s correlation test showed there was no statistical correlation between STK10 and LGALS9." (PMID 35501867, 2022). "The results showed that lack of host Stk10 results in accelerated proliferation of the tumor xenografts." (PMID 36421382, 2022).
tumor (continued). "Subsequently, we tested the expression of STK10 in PRAD by analyzing the RNA-seq data obtained from the TCGA database, and found that STK10 was abundantly expressed in 24 kinds of immune cells infiltrated in PRAD samples, especially in the T cells, the pivotal effector in the anti-tumor response." (PMID 36421382, 2022). "The results showed that the targeted deletion of host Stk10 does not affect the percentage of tumor-infiltrated neutrophile granulocytes (CD45+CD11b+Gr-1+), macrophages (CD45+CD11b+F4/80+), NK cells (CD45+NK1.1+), NKT cells (CD45+NK1.1+CD3+) and B cells (B220+)." (PMID 36421382, 2022). "Our data showed that lack of host Stk10 significantly potentiated RM-1 tumor growth in vivo." (PMID 36421382, 2022).
STK10 also shares sentences with these, for which no sentence is quoted: acute myeloid leukemia (1 paper); cervical cancer (1); hematological diseases (1); liver diseases (1); lymphoma (1); melanoma (1); Obesity (1); peripheral T-cell lymphoma (1); plasmacytoma (1); prostate tumor (1).